EGF (epidermal growth factor)
Diseases named in the same sentence as EGF in open-access papers (continued):
Sharing a sentence is not in itself a finding about the gene and the disease.
cancer (continued). "Epidermal growth factor has been demonstrated to enhance ovarian epithelial cell proliferation, facilitate EMT, elevate cancer cell invasiveness and drug resistance, and negatively impact patient differentiation and prognosis." (PMID 40612060, 2025). "The overexpression of miRNA-21 in sputum, a well-recognized anti-apoptotic factor regulated by epidermal growth factor (EGF), has been shown to effectively distinguish non-small cell lung cancer (NSCLC) patients from cancer-free individuals." (PMID 40430112, 2025). "EGFR is expressed in 25–75% of CRC cases, and its ligands, EGF and TGF-α, are found at higher levels in the mucosa surrounding malignant tumors than in the normal mucosa." (PMID 39852970, 2025). "Angiogenesis is now a crucial target in cancer therapy, focusing primarily on the VEGF/VEGFR, PDGF/PDGFR, EGF/EGFR, and FGF/FGFR signaling pathways." (PMID 40251641, 2025). "Previous studies illustrated that 1,25-(OH)2D3 suppresses cancer cells proliferation and promotes their differentiation, primarily by antagonizing TGF-β, Wnt/β-catenin, and EGF signaling pathways." (PMID 40109862, 2025). "It is a therapeutic vaccine for non-small cell lung cancer (NSCLC) that works by inhibiting the action of epidermal growth factor (EGF), a key driver of cancer cell proliferation." (PMID 40872964, 2025). "We also added blocking antibodies against VEGFR3, TGF-β, EGF, PDGF, and adrenomedullin to cancer cells before starting CM generation, which was subsequently transferred to the HLECs." (PMID 41249124, 2025). "We have shown that the mechanism involved appears to be through cytokines such as EGF, PDGF, TNF-α, IFN-γ or IL-6, which activate signaling pathways within the cancer cells themselves that lead to FN1 production." (PMID 40096084, 2025). "EGF exerts its effects through binding to the EGF receptor (EGFR), and its signaling pathways play essential roles in cancer development and anti-cancer therapies." (PMID 40733034, 2025). "Concurrently, markers like HGF, EGF, MMP–1 and the scavenger receptor CD36 reflect processes of chronic inflammation, tissue remodeling, and metabolic reprogramming, which facilitate cancer cell proliferation and survival." (PMID 41194922, 2025). "P. gingivalis induces the secretion of many cancer-contributing chemokines and cytokines, including Interleukin (IL)-1β, IL-6, IL-8, transforming growth factor (TGF)-β1, epidermal growth factor (EGF), and tumor necrosis factor alpha (TNF-α)." (PMID 41471188, 2025). "Growth factors, including platelet-derived growth factor (PDGF), epidermal growth factor (EGF), insulin-like growth factor (IGF), and TNF-α, are critical bioactive molecules that play a vital role in promoting cancer cell proliferation." (PMID 40098612, 2025). "The EGF/MAPK signaling pathway is notably active in a variety of malignancies, positioning it as a pivotal target for cancer therapeutics." (PMID 40190348, 2025). "We showed that 1 μM osimertinib, an FDA-approved anti-cancer drug/EGFR inhibitor, significantly blocked the EGF-stimulated OAT3 activity." (PMID 40733034, 2025). "In a different study, the Silica Immunoinformatics approach was used to construct a multifunctional vaccine for NSCC cancer that included MHC I, MHC II, CTL, and B-cell epitopes obtained from MAGE-A3 cells, EGF, and MUC-1." (PMID 40453095, 2025). "TAMs also produce EGF which can increase cancer cell migration and invasion by binding to EGFR expressed on cancer cells." (PMID 40376304, 2025). "There are many cytokines and chemokines that can facilitate cell fusion; however, the most relevant to cancer are platelet-derived growth factor (PDGF), tumor necrosis factor alpha (TNF-α), epidermal growth factor (EGF), and interleukin-4 (IL-4)." (PMID 40723152, 2025). "Neutrophils also contribute to cancer progression by releasing cytokines and growth factors, such as IL-6, TNF, epidermal growth factor, hepatocyte growth factor (HGF), and platelet-derived growth factor." (PMID 40027124, 2025).
cancer (continued). "Unlike many cancer vaccines designed to elicit potent CTL responses, CIMAvax-EGF intends to starve cancer cells overexpressing epidermal growth factor receptor (EGFR) through the generation of neutralizing antibodies against its cognate ligand, EGF." (PMID 41542091, 2025). "In this study, Lgr5+ cancer stem cells induced high OX40 expression and subsequent protumor signaling in ECs through paracrine EGF." (PMID 40026246, 2025). "Among the pathways most affected by statin-induced changes in kinase phosphorylation are insulin signaling, EGF–EGFR signaling, PI3K/AKT signaling, and the PD-L1/PD-1 immune checkpoint pathway in cancer." (PMID 40832614, 2025). "TAMs secrete factors such as TGF-β, EGF, Interleukin (IL)-6, and Tumor Necrosis Factor (TNF)-α, thereby promoting EMT and invasion of cancer cells, supported by in vitro and in vivo studies." (PMID 41465584, 2025). "Improper activity or inactivity of specific signaling pathways such as EGF-Ras-MAPK can lead to dedifferentiation and cancer." (PMID 40191442, 2025). "EGF, a vital growth factor, binds to EGFR on cancer cells, activating MAPK/ERK and PI3K/AKT pathways, ultimately promoting PD‐L1 gene transcription." (PMID 39258533, 2025). "Our BsAb inhibited EGF-induced activation of EGFR in CaOV3 and SKOV3, as well as blocked EGF-induced activation of VEGFR2 in CaOV3 and PA-1 OC cancer cell lines." (PMID 40969763, 2025). "This activation is initiated by the binding of epidermal growth factor (EGF) to the extracellular domain of EGFR, which is also the target region of cancer drugs like Cetuximab." (PMID 40332084, 2025). "The silencing of MTDH significantly lowered proteins found in gene sets involved in cancer-related pathways such as VEGFA-VEGFR2 and EGF-EGFR signaling, which are crucial for angiogenesis and cell proliferation." (PMID 41286067, 2025). "For example, cancer cells overexpressing cyclooxygenase 2 (COX2) and heparin bind to enzymes, such as epidermal growth factor, that help the cells cross the blood–brain barrier." (PMID 41374424, 2025). "In in vitro studies on MDA-MB-231 cancer stem cells, TQ inhibited Wnt3a and PI3K and blunted the stimulatory effects of VEGF, EGF, and FGF." (PMID 38468988, 2024). "We have identified frequently used markers for the determination of cancer cells and CSCs: Axl, CD44, CD90, CD117, CD276, EGF, PD-L1, PD-1, Sox2." (PMID 38664641, 2024). "After stimulation with EGF, the CSK protein’s activity was also different, but the activity of the CSK protein in A549 cancer cells was significantly higher than that of normal BEAS-2B cells." (PMID 38667199, 2024). "EnrichR pathway enrichment analysis coupled with Wiki Pathway datasets revealed pathways regulating multiple cellular processes that are commonly upregulated in cancers, such as VEGFA-VEGFR2 Signaling, PI3K-Akt signaling, and EGF/EGFR signaling." (PMID 38464090, 2024). "In this study, we investigate the cellular mechanisms underlying acquired resistance using trastuzumab-sensitive and -resistant cancer cells (BT474 and BT474R) treated with endogenous ligands EGF and HRG across time." (PMID 38339304, 2024). "In in vitro studies on MDA-MB-231 cancer stem cells, TQ inhibited Wnt3a and phosphatidylinositol-3 kinase (PI3K) and blunted the stimulatory effects of VEGF, EGF, and FGF." (PMID 38468988, 2024). "EGF is a proinvasive factor that activates the EGFR-ERK pathway, leading to the induction of EMT of cancer cells, cancer cell invasion and metastasis." (PMID 39003350, 2024). "In proliferating cancer cells, 20-HETE levels increase the level of growth factors such as vascular endothelial growth factor (VEGF), epidermal growth factor (EGF), fibroblast growth factor (FGF), and platelet-derived growth factor (PDGF)." (PMID 39959811, 2024).
cancer (continued). "Our studies further reveal the many facets of IQGAP1’s role in mediating EGF signaling, hence indicating the potential of targeting IQGAP1 for novel anti-cancer therapies that can supplement the existing anti-EGFR chemotherapy." (PMID 39357822, 2024). "Excessive activation of ERs has been shown to upregulate genes responsible for synthesizing growth factors, such as insulin-like growth factor-1 (IGF1) and epidermal growth factor (EGF), both of which promote the growth of cancer cells." (PMID 39659890, 2024). "One modality is through inhibition of cell cycle regulators enzymes of cancer cells such as inhibition of CDKs and DHFR enzymes, epidermal growth factor (EGF), Ras, and Tubulin proteins." (PMID 38365746, 2024). "Through cell cycle dysregulation and increased cancer cell survival, the interaction of EGFR with TGFα and EGF promotes tumorigenesis." (PMID 39590368, 2024). "The ErbB signaling pathways (ErbB receptor-mediated Ras-MAPK and PI3K-AKT pathways) have been modeled using mass action kinetics to study the effect of epidermal growth factor (EGF), heregulin (HRG) and other ligands in cancer cell mitogenesis." (PMID 39507514, 2024). "Desmoglein-1 also suppresses the EGF-induced EGFR-dependent formation of invadopodia, actin-based protrusions formed by cancer cells to facilitate invasion and metastasis." (PMID 39594667, 2024). "Girdin can participate in pancreatic cancer (PaCa) migration mediated by EGF signal, and SCU can inhibit cancer invasion by inhibiting Girdin, thus playing a role in anti-cancer." (PMID 38436812, 2024). "For example, the EGF and EGFR genes are important for cancer cell proliferation and spread in the body." (PMID 38811597, 2024). "From the perspective of cancer cells, HAT down-regulated the expression of TGF-β, TNF-α, EGF, CCL2, CXCL1, and CXCL12, crucial angiogenic and chemotactic factors for ECs." (PMID 38338342, 2024). "Thus, the EGF/EGFR signaling pathway may represent an important molecular target in cancer therapy." (PMID 39518052, 2024). "As a result, EGF and its receptor (EGFR) are targets for cancer therapies, with several EGFR inhibitors having been developed to block the proliferative signals in cancer cells." (PMID 39064802, 2024). "Additionally, EGF secretion by cancer-associated fibroblasts could contribute to resistance in neighboring cancer cells, a challenge that erlotinib, unlike other EGFR inhibitors tested, could overcome." (PMID 38893104, 2024). "Growth factors, such as epidermal growth factor (EGF) and vascular endothelial growth factor (VEGF), stimulate cancer cell proliferation, survival, and angiogenesis." (PMID 39597826, 2024). "Cancer cells secrete CSF1, thereby stimulating macrophages to produce EGF which in turn triggers the migration of cancer cells." (PMID 39003350, 2024). "Inhibiting the MAPK or WNT signaling pathways prevents the upregulation of PD-L1 protein induced by EGF (epidermal growth factor) and IFN-γ, making cancer cells resistant to chemotherapy and conventional cancer treatments." (PMID 38762484, 2024). "Upon EGF treatment, CGN c.3560C > T induced significantly higher expression of GTP-Rac1 than WT in cancer cells." (PMID 38424547, 2024). "Upon stimulation with EGF, EGFR activity is known to induce IRF1 gene cascades, largely through STAT1 phosphorylation/activation, in other cancer cell lines." (PMID 38339304, 2024). "Amphiregulin (AREG) is a member of the epidermal growth factor (EGF) family, which activates the EGF receptor (EGFR), influencing multiple tumorigenic characteristics of cancers." (PMID 39452130, 2024). "These phosphorylated tyrosine residues are bound to several adaptor proteins, and the EGF/EGFR signaling pathway is activated, which plays a critical role in cancer cell proliferation." (PMID 39518052, 2024).
cancer (continued). "Once recruited, MDSCs cluster around the original tumor, promoting EMT, creating cancer stem cell-like cells, and disseminating cancer cells through the activation of TGF-β, COX2, and the secretion of EGF and HGF." (PMID 38244071, 2024). "EMT programs in cancer are activated by various signaling molecules, including TGF-β, epidermal growth factor (EGF), and Hepatocyte growth factor (HGF)." (PMID 38939095, 2024). "This protein interacts with the EGF/TGF-α receptor to promote the growth of normal epithelial cells and inhibits the growth of some aggressive carcinoma cell lines." (PMID 38392212, 2024). "In that study, we induced EMT in the cancer cell lines via treatment with TGF β1, EGF, or TNF-α for up to 7 days with analysis conducted using single-cell RNA-sequencing." (PMID 38067396, 2023). "Secreted inflammatory cytokines in cancer cells, including IL-22, IL-6, IL-8, IL-4, IL-1β, HGF, IGF-1, EGF, G-CSF, TNF-α, VEGF, and IL-11, can confer the promotion of chemo- and radioresistance." (PMID 38140352, 2023). "Previous studies have indicated that several modulates can regulate specific EGF downstream targets, for example, TMEM16A, a dysregulated gene in many cancer types." (PMID 37309001, 2023). "Other EMT inducers, such as EGF and TNF-α, have also been targeted for therapies with the goal of attenuating EMT and cancer metastasis." (PMID 38067396, 2023). "Plasma growth factor levels were analyzed in surgical cancer patients, including hepatocyte growth factor (HGF), epidermal growth factor (EGF), and insulin-like growth factor-1 (IGF-1)." (PMID 38067195, 2023). "Gene expression analysis identified a large number of differentially expressed genes after AV25R exposure and significant differentially regulated cancer-related signaling pathways, such as VEGFA-VEGFR2 signaling and the EGF/EGFR pathway." (PMID 38138609, 2023). "In this study, we developed a live cell-based biosensor for the monitoring of the EGF-EGFR interaction, which is a crucial biomarker in cancer diagonostics as well as treatments." (PMID 36979595, 2023). "In response to epidermal growth factor (EGF) and its activated receptor (EGFR), PPAR β/δ protein levels and stability are increased via the recruitment of HSP90 (heat shock protein 90) in cancer cell lines." (PMID 37048084, 2023). "Chemotaxis plays an important role in the migration of cancer cells and subsequent metastasis toward chemotactic molecules such as CXCL12 and EGF." (PMID 36829763, 2023). "PRELP treatment has been shown to suppress cancer progression by inhibiting the TGF-β and EGF pathways leading to the control of the EMT." (PMID 37730606, 2023). "MT4-MMP is thought to stimulate cell proliferation by interacting with EGFR and enhancing its activation by its ligands, the epidermal growth factor (EGF), and tumor growth factor (TGF) in cancer cells." (PMID 37373092, 2023). "In in vitro studies, the co-stimulation of EGF and HGF (hepatocyte growth factor) showed a synergistic effect on cell proliferation in cancer cells expressing both MET and EGFR (epidermal growth factor receptor)." (PMID 38137393, 2023). "TRAF4 has been reported as a positive regulator for cell growth/proliferation pathways (AKT, ERK1/2, and ERK5) induced by EGF, TGF-β, and IL-17A signaling, contributing to the proliferation and migration of cancer cells." (PMID 37607012, 2023). "For example, one of the most used targets with this mechanism was the receptor for the epidermal growth factor (EGFR), which can be overexpressed in different types of cancer, such as colon, neck, and head, ovary, and lung, among others." (PMID 37371712, 2023). "In these cancer cells, (R)-9-HSA upregulates p21WAF1, inhibits cell growth by targeting histone deacetylase 1, and interferes with EGF signaling." (PMID 37241793, 2023).
cancer (continued). "In the case that the cancer cells acquire resistance to ADT as CRPC, however, the expression of HS3ST1 and 3-OS HS is upregulated, facilitating the binding of EGF and HB-EGF to EGFR via 3-OS HS." (PMID 37463954, 2023). "For example, the molecular targets of ADAM10 and ADAM17 in inflammation and cancer are tumor necrosis factor-alfa (TNF alfa), inteleukin-6 (IL-6), ICAM-1 and epidermal growth factor (EGF)." (PMID 37185715, 2023). "Tumour metastasis is defining characteristic of advanced cancer stage, TAM-derived EGF accelerates metastasis by activating the EGFR-ERK signaling and inhibiting the expression of lncRNA LIMT in the epithelial ovarian cancer." (PMID 37965573, 2023). "MCM7 phosphorylation (Y600) through the epidermal growth factor/Lyn kinase cascade enhances MCM complex assembly and cancer cell proliferation." (PMID 37517032, 2023). "BDNF and EGF act on downstream receptors [tropomyosin receptor kinase b (TrkB) and EGFR] on the surface of cancer cells and activate pathways ensuring cancer cell invasiveness." (PMID 37056723, 2023). "In the ErbB signaling pathway, EGF and its receptor activate MMP9, a protease involved in the proliferation of tumors, resulting in the invasion of cancer cells." (PMID 37311820, 2023). "The secretion of certain growth factors, including TGF-β and epidermal growth factor (EGF), can also lead to increased cell proliferation and decreased responsiveness to signals that usually trigger programmed cancer-cell death." (PMID 38077386, 2023). "Gene expression analyses provided insights into the molecular mechanisms underlying AV25R’s effects, revealing a multitude of differentially expressed genes and significant regulation of cancer-related pathways such as VEGFA-VEGFR2 and EGF/EGFR." (PMID 38138609, 2023). "The activation of HIF-1 in tumors promotes the metastasis of cancer cells by inducing the activation of oncogenic growth factors such as TGF-β3, epidermal growth factor (EGF) and others." (PMID 37501379, 2023). "Previous studies have demonstrated that TGFα is a more potent agonist for EGFR than EGF in various biological systems, highlighting the significance of CAF-derived TGFα in regulating EGFR-mediated cancer cell chemoresistance." (PMID 37821657, 2023). "Cyclin D1, epidermal growth factor (EGFR) and vascular endothelial growth factor (VEGR) are common carcinogenic proteins that have potential therapeutic targets in various cancers." (PMID 38414954, 2023). "Although both EGF and NGF have the same historical and tissue origin, these factors have opened separate windows in new fields of science, leading to modern cancer biology and neurobiology, respectively." (PMID 36830741, 2023). "The roles of EGF and EGFR in human cancer have been extensively reviewed with an emphasis on their clinical significance including consideration of multiple inhibitory strategies targeting EGFR activity for cancer therapeutics." (PMID 36979595, 2023). "Stronger effects have been found for sE-cad as compared to EGF, the classical ligand of EGFR, in increasing cancer cell proliferation and metastasis." (PMID 37760996, 2023). "In the case of the EGF, a self-antibody response against this molecule would diminish the serum availability of EGF, thus reducing EGFR activation and, in consequence, cancer-cell proliferation." (PMID 37241784, 2023). "The primary pro-inflammatory cytokines related to the development of cancer cachexia are TNF-α, interleukin (IL)-1 beta, IL-6, epidermal growth factor (EGF), transforming growth factor (TGF)-β, and platelet-derived growth factor (PDGF)." (PMID 37571328, 2023). "The insulin-like growth factor (IGF), epidermal growth factor (EGF), hepatocyte growth factor (HGF), and vascular endothelial growth factor (VEGF) are some major growth factor pathways used in trophoblast and cancer cells." (PMID 36834865, 2023).